FKBP1B (FKBP prolyl isomerase 1B)
Description:
Has the potential to contribute to the immunosuppressive and toxic effects of FK506 and rapamycin. PPIases accelerate the folding of proteins. It catalyzes the cis-trans isomerization of proline imidic peptide bonds in oligopeptides.
Synonyms: FKBP12.6; FKBP1L; FKBP9; OTK4; PPIase; PKBP1L
Tractability: Small molecule: a structure with a bound ligand is known; a high-quality ligand is known; it belongs to a druggable protein family. PROTAC: its protein half-life has been measured; a small molecule that binds it is known.
Target class: Isomerase; Enzyme
Gene: Protein-coding gene on chromosome 2 (24,049,701 to 24,063,681, forward strand). Ensembl gene ENSG00000119782.
Subcellular location: Cytoplasm; Sarcoplasmic reticulum
Subcellular location (Human Protein Atlas): Golgi apparatus; Vesicles; Basal body; Cytosol; Primary cilium
Pathways (Reactome):
Muscle contraction: Ion homeostasis
Transport of small molecules: Stimuli-sensing channels
Gene Ontology:
Molecular function: calcium channel inhibitor activity; calcium channel regulator activity; FK506 binding; peptidyl-prolyl cis-trans isomerase activity; protein binding; signaling receptor binding; transmembrane transporter binding
Biological process: calcium-mediated signaling; negative regulation of calcium-mediated signaling; negative regulation of release of sequestered calcium ion into cytosol; regulation of cardiac muscle contraction by regulation of the release of sequestered calcium ion; regulation of release of sequestered calcium ion into cytosol by sarcoplasmic reticulum; response to redox state; 'de novo' protein folding; negative regulation of heart rate; protein folding; protein maturation; protein refolding; regulation of ryanodine-sensitive calcium-release channel activity
Cellular component: calcium channel complex; cytoplasm; membrane; Z disc; sarcoplasmic reticulum membrane; sarcoplasmic reticulum
Genetic constraint (gnomAD): Loss-of-function variants: 4 observed, 10.1 expected, observed/expected ratio (o/e) 0.4, 90% interval 0.19 to 0.91. The upper end of that interval is the gene's LOEUF score, 0.91, which puts it in group 3 of 6, group 1 being the genes least tolerant of losing a copy. Missense variants: 90 observed, 130.48 expected, observed/expected ratio (o/e) 0.69, 90% interval 0.58 to 0.82. Synonymous variants: 53 observed, 48.97 expected, observed/expected ratio (o/e) 1.08, 90% interval 0.87 to 1.36.
Homologues: Orthologues: chimpanzee FKBP1B (100% identical), dog FKBP1B (100% identical), guinea pig FKBP1B (100% identical), macaque FKBP1B (100% identical), pig FKBP1B (100% identical), mouse Fkbp1b (97% identical), zebrafish fkbp1b (92% identical), rabbit FKBP1B (89% identical), Drosophila melanogaster Fkbp12 (70% identical), rat Fkbp1b (67% identical), Caenorhabditis elegans fkb-5 (42% identical), Caenorhabditis elegans fkb-4 (34% identical). Paralogues in human: FKBP1A (83% identical), FKBP1C (80% identical), FKBP5 (45% identical), FKBP10 (44% identical), FKBP4 (44% identical), FKBP3 (43% identical), FKBP9 (42% identical), FKBP2 (40% identical), FKBP15 (34% identical), FKBP11 (31% identical), FKBP7 (29% identical), FKBP14 (28% identical), and 6 more.
Diseases named in the same sentence as FKBP1B in open-access papers:
FKBP1B is named in the same sentence as 53 diseases in open-access papers, as found by Europe PMC text mining. Sharing a sentence is not in itself a finding about the gene and the disease. The quoted sentences say what the papers report.
cardiac hypertrophy (3 papers, 2017 to 2021). "For example, Fkbp1b modulates the calcium release from sarcoplasmic reticulum in cardiomyocyte and disruption of Fkbp1b results in cardiac hypertrophy in male mice." (PMID 28790436, 2017).
glioma (3 papers, 2020 to 2025). A benign or malignant brain and spinal cord tumor that arises from glial cells (astrocytes, oligodendrocytes, ependymal cells). "For example, the redox-associated genes NCF2, VASN, FKBP1B, and TXNDC2 have been identified as central genes, potentially serving as a dependable prognostic indicator for the clinical management of glioma." (PMID 41049606, 2025). "MAPK3 and CX3CL1 were strongly positive; NFE2L2, HSP90AB1, and SUPT20H were moderately positive; and FKBP1B, BIRC5, NPC1, IKBKE, BID, and PTEN were weakly positive in glioma tissue relative to their expression levels in normal tissue." (PMID 33194668, 2020).
memory impairment (3 papers, 2018 to 2022). "Furthermore, one paper reported gene therapy approaches, and found that increasing FKBP1b reversed calcium dysregulation and memory impairment in aging rats, allowing for them to perform as well as young rats on a memory task." (PMID 35626321, 2022). "In addition, to determine whether long-term (LT) FKBP1b overexpression is safe and efficacious and may be a candidate preventive therapy, we compared ST hippocampal FKBP1b overexpression with LT FKBP1b overexpression, which is initiated in midlife when memory impairment first begins to emerge." (PMID 29255009, 2018).
diabetes (2 papers, 2013 to 2014). "STZ treatment also suppressed expression of a wide range of genes linked with key β-cell functions or diabetes development, such as G6pc2, Slc2a2 (Glut2), Slc30a8, Neurod1, Ucn3, Gad1, Isl1, Foxa2, Vdr, Pdx1, Fkbp1b and Abcc8, suggesting global β-cell defects in STZ-treated islets." (PMID 23828045, 2013).
ovarian carcinoma (2 papers, 2021 to 2023). A malignant neoplasm originating from the surface ovarian epithelium. "PAX9 and FKBP1B are differentially methylated in cisplatin-resistant ovarian cancer cells." (PMID 34454589, 2021).
Alzheimer disease (1 paper, 2022). A progressive, neurodegenerative disease characterized by loss of function and death of nerve cells in several areas of the brain leading to loss of cognitive function such as memory and language. "Microarray studies revealed that FKBP1b gene expression was downregulated in the hippocampus of aging rats and in early Alzheimer’s disease patients." (PMID 35626321, 2022).
astrocytomas (1 paper, 2017). "Given that FKBP1A is a component of the EGFR/FKBP1A/HIF-2α pathway, which plays a role in childhood high-grade astrocytomas, increased FKBP1B levels may also cause astrocytomas." (PMID 28394947, 2017).
Cognitive impairment (1 paper, 2018). Abnormal cognition is characterized by deficits in thinking, reasoning, or remembering. "SIGNIFICANCE STATEMENT Previously, we found that hippocampal overexpression of FK506-binding protein 12.6/1b (FKBP1b), a negative regulator of intracellular Ca2+ responses, reverses both aging-related Ca2+ dysregulation and cognitive impairment." (PMID 29255009, 2018). "Another goal of the present study was to test whether LT FKBP1b overexpression in middle-aged animals could prevent the emergence of cognitive impairment as effectively as ST FKBP1b can reverse it." (PMID 29255009, 2018).
colorectal cancer (1 paper, 2023). A primary or metastatic malignant neoplasm that affects the colon or rectum. "Both FKB prolyl isomerase 1B (FKBP1B) and peroxiredoxin 5 (PRDX5) had higher plasma levels in lung- and colorectal cancer as compared to all the other cancers and were also selected independently by the models for both of these cancer types." (PMID 37463882, 2023).
fungal infection (1 paper, 2018). "The NMT1/2 and MetAP2 genes’ targeting miR-132-5p was found to be associated with fungal infection of human dendritic cells with Candida albicans and Aspergillus fumigatus and regulates immune responses through the interactions with FKBP1B, KLF4, and SPN genes." (PMID 29579063, 2018).
hearing loss (1 paper, 2022). "Three autophagy-related genes (Dram1, Fkbp1b, and Fos) were differentially expressed in the mild hearing loss group, whereas five autophagy-related genes (Dram1, Fkbp1b, Fos, Capn2, and Eef2) were differentially expressed in the severe hearing loss group." (PMID 35463035, 2022).
myeloma (1 paper, 2023). "However, FKBP12.6 (FKBP1B mRNA) is not expressed in myeloma cells and therefore not relevant for these experiments." (PMID 36717825, 2023).
prostate carcinoma (1 paper, 2015). A carcinoma that arises from epithelial cells of the prostate gland. "Of these 8 secretion-related genes, 5 genes (FKBP1B, SCIN, SMPD3, STEAP2, and TRIM36) has been associated with prostate cancer and hyperplasia." (PMID 26113971, 2015).
infection (1 paper, 2025). The state of being infected such as from the introduction of a foreign agent such as serum, vaccine, antigenic substance or organism. "Interestingly, FKBP1B and FOXO1 are also related to cardiac function, but contrary to TNNI3 they are increased in the LC group, suggesting their potential involvement in the long-term cardiac dysfunction instead of the acute phase of the infection." (PMID 40247373, 2025).
FKBP1B also shares sentences with these, for which no sentence is quoted: heart failure (11 papers); Arrhythmia (7); Ventricular arrhythmia (3); cancer (2); cardiac diseases (2); catecholaminergic polymorphic ventricular tachycardia (2); pulmonary hypertension (2); tumor (2); aortic insufficiency (1); atrial fibrillation (1); brain tumor (1); cardiac arrest (1); cardiac arrhythmia (1); cardiomyopathy (1); cognitive decline (1); colon tumor (1); death (1); Dengue (1); diffuse intrinsic pontine glioma (1); dilated cardiomyopathy (1); Early Repolarization Syndrome (1); fibrodysplasia ossificans progressiva (1); Hyperglycemia (1); Hypertension (1); hypertrophic cardiomyopathy (1); hypertrophy (1); idiopathic dilated cardiomyopathy (1); Infertility (1); ischemia (1); lung carcinoma (1).
A further 9 diseases each share a sentence with FKBP1B in 1 paper.